BRCA2 (BRCA2 DNA repair associated)
Diseases named in the same sentence as BRCA2 in open-access papers (continued):
Sharing a sentence is not in itself a finding about the gene and the disease.
breast cancer (continued). "It is currently unknown how these alleles are associated with different breast cancer subtypes in BRCA1 and BRCA2 mutation carriers defined by estrogen (ER) or progesterone receptor (PR) status of the tumour." (PMID 22053997, 2011). "It has been repeatedly shown, that the majority of BRCA1-mutated breast carcinomas (BC) do not express ER, while the hormonal receptor pattern in BRCA2-associated BC is similar to sporadic cases." (PMID 21819606, 2011). "We used DNA–damaging agents to disturb gene expression profiles of cell-lines derived from blood of patients, and we compared patterns from women with BRCA1 and BRCA2 mutations to women familial breast cancer families without such mutations." (PMID 20174566, 2010). "Not all of the breast cancer-associated SNPs assessed have been found to modify risk in carriers, however, and some of the risk associations are specific for BRCA2 mutation carriers only and not BRCA1." (PMID 21114847, 2010). "A similar idea seems to have guided an investigation of the CHEK2 gene in breast cancer that was carried out using non-carriers of BRCA1 or BRCA2 mutations." (PMID 21187953, 2010). "For BRCA2, a study has provided evidence that mutation in a ~3.3 kb nucleotide region of exon 11 (denoted the ovarian cancer cluster region, OCCR) is associated with a higher incidence of ovarian cancer relative to breast cancer." (PMID 20579331, 2010). "We were able to accurately classify BRCA1 and BRCA2 samples, and our results supported other reported findings that suggested familial breast cancer patients without BRCA1/2 mutations are genetically heterogeneous." (PMID 20174566, 2010). "The Breast Cancer Information Core Database (BIC database), a public archive of BRCA mutations, has collected the whole series of BRCA1 and BRCA2 coding variants, amounting up until now to about 1,300 deleterious mutations in the two genes, identified from various population studies." (PMID 24281179, 2010). "We studied 2208 parents and siblings of 504 unselected population-based Caucasian women with breast cancer diagnosed before age 35 years (103 from USA, 124 from Canada and 277 from Australia), 41 known to carry a mutation (24 in BRCA1, 16 in BRCA2 and one in both genes)." (PMID 20877337, 2010). "In addition, the segregation analysis of Antoniou and colleagues estimated similar polygenic variances of breast cancer risk for BRCA1 and BRCA2 mutation carriers." (PMID 20482762, 2010). "We have previously reported a novel method of using expression arrays and the Cancer Genetic Markers of Susceptibility (CGEMS) Breast Cancer Whole Genome Association Scan to prioritize IR response genes that potentially modify breast cancer risk in BRCA1 and BRCA2 carriers." (PMID 20174566, 2010). "Although protection against BRCA1-associated breast cancer and BRCA2-associated gynaecologic cancer was suggested, neither effect reached statistical significance." (PMID 20961453, 2010). "Microarray analysis has been reported to successfully predict estrogen receptor and lymph-node status of breast cancer, to distinguish between cancers associated with BRCA1 or BRCA2 mutations and to identify subclasses of breast cancer and predict outcome based on gene expression patterns." (PMID 20840765, 2010). "Several reports suggested that women with germline mutations in BRCA1 are more likely to die from their disease than are women with sporadic breast cancer, whereas BRCA2 mutation carriers and non-mutation carriers seem to share a similar prognosis." (PMID 20219108, 2010).
breast cancer (continued). "For families with multiple cases of breast cancer currently attending cancer genetics services in Australia, at most 20% of those screened for BRCA1 and BRCA2 are found to carry mutations, which is similar to the rates in the United Kingdom and the United States." (PMID 21182766, 2010). "However, the number of breast cancer patients with mutation screening and pathology information was too small to estimate directly the precise contribution of BRCA1 and BRCA2 mutations to the FRRs by tumour subtype." (PMID 20146796, 2010). "A similar study used short-term fibroblast cultures from skin biopsies from 10 BRCA1 and 10 BRCA2 mutation carriers and 10 individuals who had previously had breast cancer but were unlikely to contain BRCA1/2 mutations." (PMID 20174566, 2010). "The notion could be that unique cellular mechanisms are triggered in the breast cancer cells to stimulate BRCA2 gene expression as a temporary measure to regulate the growth of the breast cancer cells." (PMID 20202217, 2010). "We observed differences in the frequency of common genetic variants of the BRCA1 and BRCA2 and their haplotypes between early-onset breast cancer cases who did and did not carry deleterious mutations in these genes." (PMID 20807450, 2010). "One potential mechanism of BRCA2 involvement in breast cancer progression may be through deregulation of the BRCA2 gene expression." (PMID 20202217, 2010). "DNA sequence variants of unknown clinical significance are regularly identified when individuals with a family history of breast cancer are screened for mutations in the BRCA1 and BRCA2 genes." (PMID 20507642, 2010). "Furthermore 60%-70% of hereditary breast cancers seem to arise secondary to germline mutations in the BRCA1 and BRCA2 genes." (PMID 20961453, 2010). "BRCA2 levels go up in many aggressively growing breast cancer cells." (PMID 20202217, 2010). "Besides ER status, other documented genetic variables important in breast cancer research include progesterone receptor status (PR), the HER2/neu receptor, and the BRCA1 and BRCA2 mutation status." (PMID 20964848, 2010). "All cases were known carriers of BRCA2*6174delT; controls were unaffected by breast cancer." (PMID 20470408, 2010). "While studying the activity of BRCA2 gene promoter in breast cancer cells, we discovered that this promoter has bi-directional activity and the product of the reverse activity (a ZAR1-like protein, we named ZAR2) silences the forward promoter at the G0/G1 phase of the cell." (PMID 20202217, 2010). "According to the Breast Cancer Information Core (BIC) database, about two thirds of germline variants identified in BRCA1 and BRCA2 are unique; the remaining ones are recurrent founder mutations which have been described in different ethnic groups and populations." (PMID 19619314, 2009). "In this study we aimed to evaluate the role of a SNP in intron 1 of the ERCC4 gene (rs744154), previously reported to be associated with a reduced risk of breast cancer in the general population, as a breast cancer risk modifier in BRCA1 and BRCA2 mutation carriers." (PMID 19920816, 2009). "We are currently testing this by sequencing the APC gene around codons 1500–1700 in hereditary breast cancer patients which tested negative for BRCA1/BRCA2 germline mutations." (PMID 19578404, 2009).
breast cancer (continued). "Germline mutations in the breast cancer genes BRCA1 and BRCA2 are related to an increased risk for breast, ovarian and other cancers in a syndrome known as hereditary breast and ovarian cancer (HBOC) which accounts for most cases of hereditary breast cancer (HBC) worldwide." (PMID 21637504, 2009). "The age of breast cancer onset was evaluated on the basis of the mutation status; 23/44 (52%) BRCA2 mutation positive and 188/464 (41%) BRCA2 mutation negative patients were 50 years or younger at the time of diagnosis." (PMID 19232099, 2009). "Consistent associations were found for BRCA1 and/or BRCA2 mutation carriers, indicating that SNPs involved in the susceptibility to develop breast cancer in the general population are good candidates to be tested as potential modifiers in BRCA1 and BRCA2 mutation carriers." (PMID 19920816, 2009). "In addition, it was found that pregnancy is a risk factor of development of breast cancer among carriers of BRCA1 and BRCA2 genetic mutations." (PMID 19254357, 2009). "In conclusion, women from high-risk breast cancer families in which a BRCA1 or BRCA2 mutation can not be found need to be counselled about their increased risk for breast cancer." (PMID 19088722, 2009). "Despite these differences in familial phenotype, the majority of families present only early onset breast cancer and there is little to indicate which gene should be targeted first for more efficient mutation screening or if in fact one of the BRCA1 or BRCA2 gene is at cause." (PMID 19352458, 2009). "In contrast, the other groups in the prospective series (familial breast cancer without demonstrable mutations and BRCA2 mutation carriers) do well – and there is no initial crossing of the curves." (PMID 19366445, 2009). "The second major susceptibility gene involved in breast cancer risk, BRCA2, was not significantly expressed in PBMCs." (PMID 19352458, 2009). "After a longer follow-up observation, breast cancer-specific rates of death were instead similar for BRCA2 mutation carriers and non-carriers." (PMID 19232099, 2009). "DEAR1 loss of expression did not correlate with BRCA1 or BRCA2 mutation, but rather, loss of expression correlated with a strong family history of breast cancer in this young cohort (r = −0.24, p = 0.0139)." (PMID 19536326, 2009). "Specifically, we compared survival rates between BRCA2 mutation carriers and non-carriers while adjusting for demographic and clinically-recognized prognostic factors in a homogenous group of Sardinian breast cancer patients." (PMID 19232099, 2009). "Between 4% and 40% of male breast cancers might result from autosomal dominant mutations, primarily BRCA1 or BRCA2 mutations." (PMID 19144122, 2009). "There is increasing evidence that the silencing of BRCA2 gene might be important in the pathogenesis of a significant proportion of sporadic breast cancers where this gene expression is often modulated." (PMID 19442290, 2009). "For the majority of tested women, a BRCA1 or BRCA2 mutation is not found, and counselling regarding breast cancer risk is based on the review of the pedigree." (PMID 19088722, 2009). "We found that BRCA1 and BRCA2 samples were more similar to each other than to familial breast cancer patients without BRCA1/2 mutations, and that the type of sequence change in BRCA1 and BRCA2 (missense or truncating) influenced gene expression." (PMID 18497862, 2008). "Subsequently, these results will be crucial in the characterization of the genetic breast cancer susceptibility profile, within familial breast cancer cases non-carriers of BRCA1/BRCA2 mutations." (PMID 18230179, 2008).
breast cancer (continued). "Subsequent population-based studies have shown that a recurrent loss of function CHEK2 mutant, CHEK21100delC is present in approximately 1% of the population and in 5% of familial breast cancer families lacking a BRCA1 or BRCA2 mutation." (PMID 18797466, 2008). "In this study, we evaluated expression of basal CKs among tumours from BRCA1, BRCA2 and non-BRCA1/BRCA2 families (families with several breast cancer patients without BRCA1 or BRCA2 mutations), and sporadic breast cancer patients." (PMID 18275599, 2008). "Consequently, a breast cancer only phenotype was found in a minority of BRCA1 mutation families (14 out of 38), but a majority of BRCA2 families (11 out of 18)." (PMID 18783588, 2008). "However, lower estimates of lifetime risk for breast cancer of 66% in BRCA1 carriers and 45% in BRCA2 carriers were reported in subsequent population-based studies of pooled data." (PMID 18402691, 2008). "Several genes are likely to be involved in breast cancer predisposition, but no susceptibility gene aside BRCA2 and BRCA1 is likely to account for a large fraction or a major increase in risk." (PMID 18597679, 2008). "Given that hereditary breast carcinoma is primarily due to germline mutations in one of two breast cancer susceptibility genes, BRCA1 and BRCA2, we have characterised the spectrum of BRCA mutations in a cohort of 37 individuals with early-onset disease (≤40 years) and no reported family history." (PMID 18431501, 2008). "411/839 (49%) BRCA1 carriers and 355/603 (59%) BRCA2 carriers had developed breast cancer." (PMID 18513387, 2008). "Where the family history is not strong, the chances of a major gene mutation (BRCA1 or BRCA2) being present are small and so too is the risk of very early-onset breast cancer." (PMID 18283300, 2008). "According to this model, genetic susceptibility to breast cancer is explained by the effects of BRCA1 and BRCA2 mutations, and the residual familial clustering is explained by the joint multiplicative effect of a large number of genes each of small effect (i.e., by a polygenic component)." (PMID 18349832, 2008). "In this study we compared LCL gene expression signatures of breast cancer cases carrying pathogenic mutations in BRCA1 or BRCA2, to familial breast cancer cases with no known BRCA1/2 mutations (BRCAX)." (PMID 18497862, 2008). "For example, a fortunate ∼20% of women carrying BRCA2 mutations associated with high-risk of breast cancer do not develop the disease." (PMID 18404214, 2008). "Indeed breast cancer penetrance estimates for BRCA2 after 60 years were significantly higher as was overall penetrance including the index case (p = 0.02)." (PMID 18513387, 2008). "We report the frequencies of these alleles in BRCA1 and BRCA2 mutation-positive cases, and compare these frequencies with mutation-negative familial breast cancer cases, as well as female French Canadian controls with no personal history of cancer." (PMID 18402691, 2008). "Of the 106 BC samples a subset of 29 group-A and 33 group-B breast samples were further studied to find out the association between the candidate genes with some breast cancer susceptibility genes like BRCA1, BRCA2 that are intermittently associated with breast cancer." (PMID 18990233, 2008). "Second corpus cancer has been observed to be in excess after primary sporadic and familial breast cancers; BRCA1, BRCA2, and E-cadherin gene may be shared genetic risk factors for the two cancer sites." (PMID 17406355, 2007).
breast cancer (continued). "Overall, there is an emerging picture indicating that breast cancer risk in BRCA1 and BRCA2 positive women are substantially higher than in the general population and the genes are considerably affected by non-genetic, environmental factors and by additional genetic modifiers." (PMID 18053234, 2007). "However, low-dose ionising radiation has recently been shown to increase the risk of breast cancer significantly among BRCA1 and BRCA2 mutation carriers." (PMID 17428320, 2007). "The absence of mutation or promoter hypermethylation in the BRCA2 gene in the majority of breast cancer cases has indicated alternative ways of its involvement, deregulated expression being one possibility." (PMID 17945002, 2007). "The two major breast cancer susceptibility genes, BRCA1 and BRCA2, have been shown to be involved in a significant proportion of families affected with breast and ovarian cancer, but it is clear that about 70% of familial breast cancer is not caused by mutations in these genes." (PMID 17760956, 2007). "Interestingly, one tumor had a medullary phenotype (on a pre-treatment biopsy), which is much more commonly a feature of BRCA1- than BRCA2-related breast cancer, although both tend to feature a continuous pushing margin." (PMID 18053174, 2007). "The role of BRCA2 in the development of the sporadic form of breast cancer remains undefined." (PMID 17945002, 2007). "Additionally, associations with OCs have been noted among some subsets of breast cancer cases, including younger women, those with a family history of breast cancer, germline mutations in BRCA1 or BRCA2, or other genetic polymorphisms." (PMID 17553133, 2007). "In addition to the high-penetrance genes BRCA1/BRCA2, rare mutations in a number of other genes, such as CHEK2, ATM, BRIP1, and PALB1 predispose to breast cancer, as do more common variants in CASP8 and TGFB1." (PMID 17916242, 2007). "Germline mutations in BRCA1 (OMIM 113705) and BRCA2 (OMIM 600185) account for familial clustering in the majority of families with both breast and ovarian cancer and in approximately one-half of families with site-specific breast cancer." (PMID 17603881, 2007). "There has been a dearth of evidence-based screening guidelines for women age < 40 with a family history of breast cancer, a BRCA1 or BRCA2 mutation, or other risk factors, largely because of the lack of randomized, controlled trials to inform the development of such guidelines." (PMID 16800895, 2006). "The mean age of breast cancer onset in males with and without BRCA2 mutations is still a controversial issue." (PMID 16764716, 2006). "Our results suggest that parity may have a similar effect on breast cancer risk among BRCA1 and BRCA2 mutation carriers." (PMID 17187672, 2006). "This difference might suggest differences in the development of breast cancer among BRCA1 and BRCA2 mutation carriers." (PMID 17187672, 2006). "There is considerable interest in whether anti-oestrogens can be used to prevent breast cancer in women bearing mutations in the BRCA1 and BRCA2 genes." (PMID 16538216, 2006). "Genetic analysis of the subjects who developed breast cancer in the NSABP P-1 Breast Cancer Prevention Trial indicates that the Gail model inefficiently identifies BRCA1 and BRCA2 mutation carriers, since only 6.6% (19/288) of that high-risk population carried such mutations." (PMID 16800895, 2006).